EGFR (epidermal growth factor receptor)
Diseases named in the same sentence as EGFR in open-access papers (continued):
Sharing a sentence is not in itself a finding about the gene and the disease.
lung cancer (continued). "And dual inhibition of MET and EGFR might be a therapeutic strategy for EGFR-driven drug resistance METex14 lung cancer." (PMID 36338758, 2022). "The ORR of patients with EGFR-mutant lung cancer who received an ICI-based regimen was 16.3%." (PMID 36082280, 2022). "Among them, EGFR were the classical kinases driving lung cancer." (PMID 35470770, 2022). "have indicated that the up‐regulation of IL‐6/STAT signal transduction may be a contributor to EGFR‐TKIs resistance in lung cancer." (PMID 35605028, 2022). "In EGFR mutant lung cancer cells, miR-206 was shown to reduce HGF-induced gefitinib resistance." (PMID 35885514, 2022). "EAI045 and cetuximab combined induce tumor regression in mouse models of EGFR-mutant lung cancer." (PMID 36145346, 2022). "Intriguingly, in EGFR-mutant HCC827 lung cancer cells subjected to prolonged gefitinib treatment in tissue culture, an acquired resistance mechanism involved MET gene amplification, Met-dependent HER3–tyrosine phosphorylation, and HER3-dependent activation of PI3K downstream of Met." (PMID 35249128, 2022). "Thus, we explored the role of EGFR/TRAF4‐mediated ERK5 activation in the proliferation of lung cancer cells." (PMID 35748027, 2022). "We have reported that exosomes from latently HIV-infected T cells interact with the epidermal growth factor receptor (EGFR) of oral and lung cancer cells for cellular entry and subsequently stimulate downstream EGFR signaling without causing EGFR activation." (PMID 36526691, 2022). "Furthermore, 6b exhibited a great anti-proliferative effect against gefitinib-resistant H1975 lung cancer cells with mutant EGFR (L858R/T790M) expression, gefitinib-resistant H1975 cells (IC50 = 3.65 μM) as compared with standard gefitinib (IC50 > 20 μM)." (PMID 36080307, 2022). "Finally, this study only predicted EGFR-mutation in LADC and excluded other lung cancer gene mutations." (PMID 36059655, 2022). "The Human Protein Atlas comparing EGFR expression among 20 cancer types reported moderate to strong immunoreactivity in 75% of patients with malignant glioma or head-and-neck cancer, followed by 64% of lung cancer patients." (PMID 35332092, 2022). "Additionally, the induction of ferroptosis can sensitize epidermal growth factor receptor (EGFR)-activating mutant lung cancer cells resistant to EGFR-tyrosine kinase inhibitors (TKIs)." (PMID 36267413, 2022). "NT157 also presented potentiating effects on EGFR inhibitors in lung cancer cells." (PMID 36224313, 2022). "A total of 4,384 patients with primary lung cancer resection performed by a single team from January 2011 to May 2020 were consecutively recorded, and fortyseven patients of them received EGFR TKI therapy." (PMID 35360423, 2022). "Herein, we report a robust fluorescent “turn-on” clutch probe based on non-emissive QDs-Ru complexes to rapidly recognize EGFR gene mutation in plasma cfDNA from lung cancer patients." (PMID 35457970, 2022). "Our data may indicate that 57 genes were involved in the development of lung diseases and were related to EGFR-TKI treatment of lung cancer." (PMID 36225197, 2022). "The immunological phenotypes in the TME of EGFR–mutated lung cancer were characterized as non-inflamed, for which immunotherapy is largely ineffective." (PMID 36482371, 2022). "The current College of American Pathologist (CAP)/International Association for the Study of Lung Cancer (IASLC)/Association for Molecular Pathology (AMP) guidelines recommend screening advanced-stage lung cancer patients for targetable alterations including testing for EGFR, ALK, and ROS12." (PMID 36057739, 2022).
lung cancer (continued). "Here in this study, it is demonstrated that CAFs in tumor tissues could strengthen the lung cancer cell proliferation and EGFR TKIs resistance through the secretion of Kyn." (PMID 35831824, 2022). "Discordant data exist in the literature concerning the prognostic value of EGFR mutation in resected lung cancer, showing both positive and negative prognostic value." (PMID 35326552, 2022). "Unlike most lung cancer cohorts in which prolonged smoking and exposure to air pollutants are clear risk factors, EGFR-mut cancers tend to occur in younger patients who are non-smokers or have had limited exposure." (PMID 35061724, 2022). "Epidermal growth factor receptor (EGFR) is an essential driver gene in lung cancer." (PMID 35844793, 2022). "Furthermore, repression or enhancement of functional ncRNAs has been used to affect the natural progression of lung cancer and reverse EGFR TKI resistance in vivo and in vitro, indicating their therapeutic value." (PMID 36139582, 2022). "Targeted therapies, however, have had a greater impact thus far because, for the subset of lung cancer patients with driver mutations (often nonsmokers), persistent response and survival extension therapy are targeted to EGFR, ALK, RAF, ROS, RET, and HER2." (PMID 36291827, 2022). "Since the successful treatment of lung cancer with the first generation of EGFR inhibitors, a new chapter in targeted therapy for lung cancer has been opened, and targeted therapy has led to improved survival rates for many patients with intermediate to advanced NSCLC." (PMID 36304772, 2022). "In lung cancer cells, silibinin could selectively reduce the dimerization of EGFR mutants and subsequently dampen their activities, but wild type EGFR was not affected." (PMID 35269825, 2022). "We found that an increased pre-treatment PLC correlated with slower lung cancer progression and longer PFS after adjusting for age, sex, smoking status, ECOG status, tumor histology, EGFR mutation, and PDL-1 expression (hazard ratio: 0.99, 95% confidence interval: 0.99–1.00." (PMID 35022510, 2022). "Next, we further explored autocrine CXCL10 expression in EGFR-mutant lung cancer cell lines." (PMID 36612121, 2022). "Targeting EGFR in glioblastoma patients with tyrosine kinase inhibitors used for the treatment of EGFR-mutated lung cancer has not shown convincing efficacy, likely because of the lack of sensitizing mutations and intratumoral heterogeneity of EGFR expression." (PMID 34998092, 2022). "We have further compared the frequency of EGFR gene mutation between the lung cancer cohort in the coal-producing areas and those of the non-coal-producing areas." (PMID 35606799, 2022). "Recent studies showed that lung cancer cells with the BIM deletion polymorphism and EGFR mutation are resistant to third-generation EGFR-TKIs, suggesting that the BIM deletion polymorphism has potential as a biomarker to predict the efficacy of third-generation EGFR-TKIs in patients." (PMID 35840984, 2022). "When comparing lung cancer patients to healthy individuals, the levels of exosomal EGFR were significant higher in five of nine lung cancer patients, while the levels of soluble EGFR in plasma were not significantly different in seven of nine lung cancer patients." (PMID 35158999, 2022). "In addition, activation of TLR2 and TLR4 induce extracellular matrix remodeling and Epithelial Growth Factor Receptor (EGFR)-mediated signaling, respectively, stimulating lung carcinoma progression." (PMID 35742983, 2022). "Most recently, a comparative study of Wi-N, CAPE, and Wi-A showed that Wi-N and Wi-A could inhibit EGFR (Epidermal Growth Factor Receptor) and its mutant forms in the EGFR-driven lung carcinoma, while CAPE could strongly inhibit wild-type EGFR." (PMID 36164647, 2022). "Cancer immunotherapy has achieved less success in EGFR mutant lung cancers." (PMID 34638461, 2021).
lung cancer (continued). "This triple sequential regimen might also be an option for EGFR mutant NSCLC, since D is approved for the treatment of EGFR mutant lung cancer." (PMID 35008514, 2021). "Targeted therapy to block CD47 was effective against wild-type and EGFR-mutant lung cancer cells." (PMID 34680249, 2021). "Likewise, single-agent MET dependence occurs both as a de novo and acquired resistance mechanism, highlighting the plasticity of EGFR-mutant lung cancers to rewire their signaling networks." (PMID 34516823, 2021). "Although the EGFR-independent antitumor effects of these agents have been reported in leukemia and squamous lung cancer patients, only a few studies have evaluated their effects on lung cancer patients." (PMID 34445227, 2021). "Likewise, a previous study reported that exon 20 mutants had higher PD‐L1 expression (48%) than HER2‐mutant (23%) or sensitizing EGFR‐mutant (22%) lung cancers." (PMID 33210451, 2021). "Thus, EGFR-mutant lung cancer cells are more sensitive to the anti-proliferative effects of vitamin D in contrast to KRAS-mutant lung cancer cells." (PMID 33652978, 2021). "In some tumours, such as HNSCC and lung cancer, inhibiting the synthesis of α-1,3/4 fucoside bonds may promote tumour progression by improving EGFR activity 149-150." (PMID 34093814, 2021). "Furthermore, mTOR inhibitors reduced the proliferating potential of EGFR mutant drug-resistant lung cancer cells." (PMID 33996789, 2021). "Based on these results, we envision that exosomal microRNAs may not only serve as predictors of the response to EGFR-TKIs but also provide an alternative approach for lung cancer interventions in heterogeneous EGFR-mutant NSCLC." (PMID 33671000, 2021). "Notably, the EGFR tyrosine kinase inhibitor resistance pathway was significantly enriched in the youth group, implying that the young lung cancer group was easier to get EGFR-TKI resistance." (PMID 35096611, 2021). "Non-small cell lung cancer (NSCLC) is a major subtype of lung cancer, and the main cause of NSCLC at the molecular level in Asian populations is an EGFR exon 19 in-frame deletion or L858R point mutation, which constitutively activate its receptor tyrosine kinase activity." (PMID 34830169, 2021). "However, agonism of the cholesterol efflux regulator LxR has been shown to sensitize lung cancer cells to epidermal growth factor receptor (EGFR) tyrosine kinase inhibitor (TKI) treatment." (PMID 34281263, 2021). "Furthermore, AuNPs loaded with EGFR siRNA to silence the expression of EGFR in M2 macrophages and lung cancer cells inhibited angiogenesis and produced lasting anti-tumor immune effects." (PMID 34588987, 2021). "Moreover, growing papers testified that EGFR is high-expression in lung cancer patients, induces excessive activation to many signaling pathways, like AKT/mTOR and MAPK/ERK." (PMID 33767988, 2021). "However, to the best of our knowledge, no study has examined the expression of both ZEB1 and BMI1 in lung cancer specimens from patients with acquired resistance to EGFR‐TKI." (PMID 33764690, 2021). "Lung cancer among never smokers is increasing in East Asians, and East Asians harboring EGFR gene mutation are far more likely to be diagnosed with lung cancer." (PMID 34682867, 2021). "Indeed, EGFR signaling in lung cancer activates the PD-1 immune checkpoint to promote immune evasion." (PMID 33807608, 2021). "Also, using a miRNA array profiling analysis, T790M/L858R-mutated lung cancer was found to have 20 up-regulated miRNAs, including miR-1 and miR-196a, compared to EGFR wild-type lung cancer." (PMID 34830377, 2021).
lung cancer (continued). "We hypothesized that phenformin, an OXPHOS complex 1 inhibitor, would selectively inhibit the proliferation of lung cancer cells with acquired EGFR-TKI resistance that mainly employ mitochondrial OXPHOS." (PMID 34367462, 2021). "Unlike patients expressing mutant KRAS, patients with lung cancer harboring EGFR mutations are relatively resistant to immunotherapy." (PMID 34038737, 2021). "However, existing EGFR-inhibitory drugs used to treat head and neck squamous cell carcinoma, lung cancer, and colorectal cancer have a limited response rate in TNBC 23, 24, and the role of EGFR in CTC clusters and polyclonal metastasis has yet to be studied." (PMID 33995681, 2021). "Therefore, research on cell lines that reflects the phenotypes of their cognate primary cancer cells is important to advance the treatment of lung cancers that express a constitutively activated EGFR." (PMID 34202566, 2021). "The treatment of lung cancer has been dramatically improved in the past 17 years with the discovery of driver oncogenes and the development of molecularly targeted drugs that bind them, including osimertinib for mutant EGFR or crizotinib for ROS1 fusions." (PMID 33846488, 2021). "Therefore, more experiments in vivo and in vitro, as well as more clinical data, are needed to explore the exact role played by H19 regulating sensitivity to the various EGFR‐TKIs used in clinical treatment of lung cancer." (PMID 33931980, 2021). "Studies have suggested that the use of second-line ICIs alone in treating lung cancer patients with EGFR mutations does not lead to good survival benefits." (PMID 34307141, 2021). "Our findings imply that exploiting PFKFB3 as an autophagy flux mediator for therapeutic purposes could represent a novel combination treatment regimen against lung cancer tumors with intrinsic or acquired resistance to EGFR TKIs." (PMID 34359849, 2021). "Besides EGFR and PIK3CA, other known mutations were detected in KRAS (n = 4; G12V, G12A, G12D, and Q61H), which have all been reported as driver mutations in lung cancer." (PMID 33407425, 2021). "Interestingly, we found that the combination of nutlin‐3 or carfilzomib and osimertinib (3rd‐generation inhibitors of EGFR T790M) were highly effective in EGFR T790M lung cancer cell line NCI‐H1975." (PMID 33188726, 2021). "Targeting to EGFR-expressing lung cancer cells is achieved by an anti-EGFR bispecific antibody." (PMID 33672261, 2021). "Tissue sampling could originally only establish the diagnosis of lung cancer, but now sufficient tissue sampling is needed for next generation sequencing for epidermal growth factor receptor (EGFR), anaplastic lymphoma kinase (ALK), ‐etc‐." (PMID 32949105, 2021). "EGFR-mutant NSCLC is the most prevalent molecular subtype in lung cancer patients." (PMID 34113560, 2021). "Epidermal growth factor receptor (EGFR) is overexpressed in lung cancer patients." (PMID 34445110, 2021). "It seems that YAP in the context of the Hippo pathway has a major role in controlling the expression of PDL1 in lung cancer, providing a link to EGFR resistance and PDL1 and rendering it an attractive target to overcome EGFR-TKI resistance in lung adenocarcinoma." (PMID 34944765, 2021). "While extensive research has shown that synergy between CALM and EGFR promotes gene transcription and cell proliferation in different cancer types, including human breast cancer, lung cancer, and astrocytic gliomas but there are rare data in regard to its role in ESCC, especially CALM1." (PMID 33602237, 2021). "However, the anticancer effects of SB in EGFR TKI-resistant lung cancer cells, and the role of signal transducer and activator of transcription 3 (STAT3) in the SB-induced apoptosis have not been elucidated yet." (PMID 34068421, 2021). "Small-molecule EGFR inhibitors, known as TKIs, have been used to treat patients with lung cancer." (PMID 34445110, 2021).
lung cancer (continued). "The presence of EGFR in lung cancer exosomes induces tolerant DCs." (PMID 34511114, 2021). "In our study, we found that worse PFS was frequent in specific DDR-altered lung cancer patients without EGFR or ALK mutations." (PMID 34604048, 2021). "Some studies have reported lack of associations between PD-L1 expression and EGFR status in lung cancer patients." (PMID 33956842, 2021). "Interestingly, miR-146a expression is significantly lower in lung cancer tissue, which suggests that it acts as a tumor suppressor via targeting EGFR expression." (PMID 34790566, 2021). "Afatnib resulted in significantly better overall survival and progression‐free survival than gefitnib and erlotinib for EGFR mutation‐positive advanced non‐small cell lung cancer patients without brain metastases." (PMID 33336895, 2021). "It has been reported that CAPN2 might promote lung cancer progression by activating EGFR/pAKT signaling pathway, and also contribute to the resistance to paclitaxel or EGFR-TKI21,22." (PMID 34728688, 2021). "EGFR gene is prominently expressed in Lung Cancer and Non-Small Cell Lung Cancer." (PMID 34764329, 2021). "Therefore, the development of new therapeutic drugs for the treatment of lung cancer patients with EGFR TKI resistance is urgently needed." (PMID 34068421, 2021). "EGFR genotyping using EV DNA derived from pleural effusion in lung cancer is a good example." (PMID 34359729, 2021). "Our study showed that TKIs could prolong ICU survival in EGFR-driven lung cancer, even for those patients with a critical illness requiring MV." (PMID 34680533, 2021). "The combination of epidermal growth factor receptor–tyrosine kinase inhibitors (EGFR-TKIs) with vascular endothelial growth factor (VEGF) blockade has been shown to produce an improved progression-free survival in patients with advanced lung cancer." (PMID 34680445, 2021). "A similar EGFR/c-METcross-talk has previously been reported in other cancers, such as lung cancer." (PMID 34550531, 2021). "Therefore, we concluded that KRAS-mutant lung cancer cells were more receptive to modulation of OPN expression by RESV than EGFR-mutant lung cancer cells." (PMID 33652978, 2021). "However, more research is now focusing on exosomal EGFR and the role it plays in the pathogenesis and progression of lung cancer." (PMID 33855679, 2021). "We showed that ≥ 50% PD-L1 positivity within the resected tumor tissue was an independent risk factor for recurrence after lung cancer surgery, whereas the EGFR mutation status was not." (PMID 34471191, 2021). "This suggests that the encapsulation in micelles, and particularly EGFR aptamers modification of micelles could efficiently mediate the uptake of Sali in EGFR-overexpressing lung cancer cells." (PMID 34452081, 2021). "Again, HA is implicated in EMT through EGF or TGF-β1 signaling in lung cancer cell line A549, where TGF-β1 upregulates HAS1, HAS2, and HAS3 expressions and augments CD44 expression interacts with EGFR, leading to the activation of the downstream signaling AKT and ERK pathways." (PMID 34976811, 2021). "In nonsmall cell lung cancer (NSCLC) without EGFR mutation, afatinib was shown to induce apoptosis via Ets-like-1 protein (Elk-1)-mediated inhibition of cancerous inhibitor of PP2A (CIP2A)." (PMID 34294686, 2021). "It was shown that lung cancer cells with the EGFR mutation are more radiosensitive than those without." (PMID 33435596, 2021). "Aberrant overexpression of the epidermal growth factor receptor (EGFR) has been detected in various malignancies, including nonsmall cell lung cancer (NSCLC), colorectal cancer (CRC), and head and neck squamous cell carcinoma (HNSCC), and is associated with a poor prognosis." (PMID 33801379, 2021). "These evidences suggested that targeting STAT3 may provide a new strategy to overcome EGFR-TKI acquired resistance in lung cancer." (PMID 33391507, 2021).